PPP2R1B (protein phosphatase 2 scaffold subunit Abeta)
Diseases named in the same sentence as PPP2R1B in open-access papers:
PPP2R1B is named in the same sentence as 40 diseases in open-access papers, as found by Europe PMC text mining. Sharing a sentence is not in itself a finding about the gene and the disease. The quoted sentences say what the papers report.
lung carcinoma (9 papers, 2013 to 2024). "As a tumor suppressor, mutations and alterations in PPP2R1B have been found in human cancers, including colon cancer, lung cancer and cervical cancer, and is involved in chemotherapy sensitivity." (PMID 34512348, 2021). "PPP2R1B linked to lung cancer has a z-score of -0.08 in breast while a FUGUE score of 0.7." (PMID 34270548, 2021). "PPP2R1B is located at chromosome 11q23.1 and is abnormally expressed in colon, breast and lung cancers." (PMID 38429738, 2024). "Consistently, the strong positive correlation between eIF3a and PPP2R1B expression was observed in melanoma, lung cancer and breast cancer." (PMID 34512348, 2021). "In addition, the correlation between eIF3a and PPP2R1B was also observed in lung cancer and breast cancer tissue, suggesting that the mechanism is universal." (PMID 34512348, 2021). "PPP2R1B encodes the beta isoform of the A subunit of the serine/threonine protein phosphatase 2A (PP2A), which has been found to be mutated also in colon and lung cancers." (PMID 28426742, 2017). "Reports of somatic mutations of the PPP2R1A and PPP2R1B genes, which encode the α and β isoforms of the structural PP2A/A subunit, were found to be associated with various human cancers, including lung cancer, colon cancer, breast cancer, skin cancer and ovarian cancer." (PMID 26684356, 2016).
breast carcinoma (6 papers, 2011 to 2025). "A particular study has shown that PPP2R1B is mutated in 13% of breast cancers, and these mutations result in defective attachment of the B and C subunits." (PMID 24460909, 2014). "Half of the breast cancers investigated had a low expression of PPP2R1B, contributing to malignant transformation." (PMID 24460909, 2014). "In fact, PPP2R1B has been described as a tumour suppressor gene as it is often found to be deleted in human breast cancer." (PMID 24460909, 2014). "We also identified a cluster associated with the extrinsic apoptotic pathway involving PPP2R1A, PPP2R1B and YWHAE, proteins dysregulated in breast cancer." (PMID 39353922, 2024).
colorectal cancer (6 papers, 2015 to 2024). A primary or metastatic malignant neoplasm that affects the colon or rectum. "Recent studies have demonstrated that the PPP2R1B gene, which encodes PP2A subunit A, is altered in human lung and colorectal carcinomas." (PMID 38429738, 2024). "And For miR-587, it can antagonize 5-FU-induced apoptosis and confers drug resistance by regulating PPP2R1B expression in colorectal cancer, and it is related to the survival time of glioblastoma multiforme patients." (PMID 32788609, 2020). "Taken together with in vitro and in vivo results, our studies demonstrate that miR-587/PPP2R1B has an important role in drug resistance of colorectal cancer." (PMID 26247730, 2015). "Importantly, studies of colorectal cancer specimens indicate a positive correlation between miR-587 expression and chemoresistance and an inverse correlation between PPP2R1B expression and drug resistance." (PMID 26247730, 2015). "Importantly, miR-587 expression positively and PPP2R1B expression inversely correlate with drug resistance in colorectal cancer patients." (PMID 26247730, 2015). "Importantly, studies of colorectal cancer specimens indicate that the expression of miR-587 and PPP2R1B positively and inversely correlates with chemoresistance, respectively, in colorectal cancer." (PMID 26247730, 2015). "Our studies have identified miR-587 as a potential target for drug resistance in colorectal cancer and suggested that modulating the PPP2R1B (PP2A)/pAKT/XIAP axis may have benefits against drug resistance." (PMID 26247730, 2015). "A previous study demonstrated that miR-587 could target the 3′UTR of PPP2R1B in colorectal cancer." (PMID 32561739, 2020).
colon cancer (5 papers, 2007 to 2024). "PPP2R1B was identified as a putative human tumor suppressor gene and mutation of PPP2R1B was observed in lung and colon cancers." (PMID 17895985, 2007). "We have identified a novel miR-587/PPP2R1B(PP2A)/pAKT/XIAP signaling axis that regulates the response of colon cancer cells to 5-FU treatment." (PMID 26247730, 2015). "In this study, we have discovered a novel miR-587/PPP2R1B (PP2A)/pAKT/XIAP signaling axis that mediates the response of colon cancer cells to 5-FU treatment." (PMID 26247730, 2015). "Inhibition of miR-587 expression or rescue of PPP2R1B expression in colon cancer cells increases their sensitivity to 5-FU treatment." (PMID 26247730, 2015). "Knockdown of PPP2R1B by siRNAs confers 5-FU resistance in colon cancer cells, mimicking miR-587 effect." (PMID 26247730, 2015). "Hence, we selected PPP2R1B for further investigation; we also found that it was negatively associated with survival in the GDC TCGA colon cancer (COAD) cohort." (PMID 38429738, 2024).
esophageal cancer (3 papers, 2016 to 2021). A primary or metastatic malignant neoplasm involving the esophagus. "Similar results were obtained in esophageal cancer cells, after inhibition of miR-200c, which saw an increase in apoptosis, sensitivity to cisplatin, and PPP2R1B expression, which encodes the β-isoform of the A subunit of another serine/threonine phosphatase PP2A, followed by a reduction of p-AKT." (PMID 34573382, 2021). "Previous studies have reported that silencing PPP2R1B enhances 5-FU resistance, and PPP2R1B overexpression increases the sensitivity of tongue squamous cell carcinoma and esophageal cancer cells to docetaxel and cisplatin, respectively by acting as an AKT phosphatase." (PMID 34512348, 2021). "However, in a study in esophageal cancer, an expression of a subunit phosphatase 2A (PPP2R1B) that negatively regulates AKT phosphorylation was increased following knockdown of miR-200c and this protein was implicated in the resistance to cisplatin." (PMID 27601996, 2016).
tongue squamous cell carcinoma (2 papers, 2021 to 2024). A squamous cell carcinoma that arises from the tongue. "In tongue squamous cell carcinoma (TSCC), exosomal miR-200c may be an effective strategy for suppressing chemoresistance to docetaxel, as it inhibits TUBB3 and PPP2R1B." (PMID 38429738, 2024).
Azoospermia (1 paper, 2022). Absence of any measurable level of sperm,whereby spermatozoa cannot be observed even after centrifugation of the semen pellet. "Regarding the reproductive system, three of these genes (UBE2N, PPP2R1B and ACVR2A) have been shown to be involved in reproductive disfunctions in humans (polycystic ovary syndrome and transsexuality, azoospermia, and susceptibility to preeclampsia, respectively." (PMID 36340025, 2022).
B-cell chronic lymphocytic leukemia (1 paper, 2016). "PPP2R1B itself has also been implicated in deregulation of cell cycle and apoptosis in B-cell chronic lymphocytic leukemia." (PMID 27846841, 2016).
brain tumours (1 paper, 2016). "Our DNA microarray analyses have identified several tumour suppressors as candidate downstream targets of TLX and TET3, including BTG2 and PPP2R1B, which were also upregulated upon TLX knockdown in PBT003-grafted brain tumours in NSG mice." (PMID 26838672, 2016).
breast tumors (1 paper, 2025). "Indeed, heterozygous loss of the PPP2R1B gene is reported in 48% of breast tumors in TCGA and 40% of tumors in METABRIC." (PMID 40178903, 2025).
gastric cancer (1 paper, 2011). A primary or metastatic malignant neoplasm involving the stomach. "We performed cDNA microarray analysis to identify the downstream target genes of SOX2 in gastric cancer cells, and found that many tumor-associated genes exhibited significant changes in expression after SOX2-overexpression (e.g., LTF, PPP2R1B, TGFBR2, SERPINE1, MMP9, HMGA1 and SOX9)." (PMID 21304604, 2011).
head and neck cancer (1 paper, 2007). A primary or metastatic malignant neoplasm affecting the head and neck. "We could not observe any mutation of PPP2R1B gene in head and neck cancer cell lines (data not shown)." (PMID 17895985, 2007).
infertile (1 paper, 2025). "Whole-exome sequencing of blood samples obtained from six members of the family, including the infertile patient, identified the heterozygous missense mutation c581G (p.R194Q) within the PPP2R1B gene." (PMID 41081447, 2025).
melanoma (1 paper, 2021). A malignant, usually aggressive tumor composed of atypical, neoplastic melanocytes. "The positive relationship between eIF3a and PPP2R1B expression was also observed in melanoma tissues." (PMID 34512348, 2021). "The results showed that the expression of eIF3a was positively correlated with PPP2R1B expression in patients with melanoma." (PMID 34512348, 2021). "Here, this study reported for the first time that eIF3a expression is positively correlated with vemurafenib sensitivity in melanoma cells, and this effect of eIF3a is mediated by regulating the translation of the protein phosphatase PPP2R1B, which inhibits ERK phosphorylation." (PMID 34512348, 2021). "Furthermore, eIF3a controlled ERK activity by regulating the expression of the phosphatase PPP2R1B via a translation mechanism, thus determining the sensitivity of melanoma cells to vemurafenib." (PMID 34512348, 2021). "In addition, consistent with other phosphatases of ERK, PPP2R1B knockdown in melanoma cell lines led to increased ERK phosphorylation and mediated the negative regulatory effect of eIF3a on vemurafenib sensitivity." (PMID 34512348, 2021).
nasal polyp (1 paper, 2012). "Notably, we found that the genes involved in the Wnt pathway were enriched (P = 0.026), and four genes (FZD5, LRP6, PPP2R1B, and TBL1XR1) in this pathway switched to proximal APA sites in nasal polyp tissue." (PMID 23185289, 2012).
non-alcoholic fatty liver disease (1 paper, 2025). "For PPP2R1B elevation, a recent study has demonstrated that the upregulation of the PPP2R1B gene, directly targeted by the transcription factor IRF3, is associated with increased dysglycemia and impaired glucose regulation in patients with obesity and non-alcoholic fatty liver disease." (PMID 40711007, 2025).
prostate carcinoma (1 paper, 2023). A carcinoma that arises from epithelial cells of the prostate gland.
pulmonary fibrosis (1 paper, 2023). Chronic progressive interstitial lung disorder characterized by the replacement of the lung tissue by connective tissue, leading to progressive dyspnea, respiratory failure, or right heart failure. "Compared with the control group, the BLM-induced pulmonary fibrosis group exhibited significantly higher expression of Fmod and Tgfbr2 mRNA; in contrast, the mRNA expression levels of Bambi, Skp1, Zfyve9, Zfyve16, Ppp2ca, Ppp2r1a, Ppp2r1b, Rps6kb1, and Rps6kb2 were markedly lower." (PMID 38259493, 2023).
retinal ischemia (1 paper, 2025). A ischemic disease that involves the retina. "A deficit in PPP2R1B might enhance inflammatory responses, exacerbating gliosis and retinal damage in diseases like DR or retinal ischemia." (PMID 40906190, 2025).
rubella (1 paper, 2023). A viral infection caused by the rubella virus. "In rubella, including five in whole blood (JAGN1, RRP12, RP11-452K12.7, CASP7, and AP3S2), four in the lung tissue (IL17RC, FAM86HP, AMACR, and RRP12), and four in the transformed fibroblast cells (PPP2R1B, C11orf1, DLAT, and TMEM117)." (PMID 37020999, 2023). "Similarly, in transformed fibroblast cells, we found PPP2R1B (padjusted = 0.022), C11orf1 (padjusted = 0.029), DLAT (padjusted = 0.045), and TMEM117 (padjusted = 0.046) as rubella-related genes." (PMID 37020999, 2023).
squamous cell carcinoma (1 paper, 2016). A carcinoma arising from squamous epithelial cells. "Potential tumor suppressor genes, also found in other squamous cell carcinomas, have been discovered in the lost regions 2q33-q37.3 (PLCD4), 3p26.3-q11.1 (RBMS3, PLCD1, and CACNA2D3) and 11q12.2-q25 (CPT1A, CCND1, FGF4/FGF3, and PPP2R1B)." (PMID 26901676, 2016).
thyroid cancer (1 paper, 2025). "They reported that LncRNA contributed to the chemosensitivity of thyroid cancer cells by modulating the miR-196a-5p/PPP2R1B signaling pathway." (PMID 40804316, 2025).
tumor (18 papers, 2007 to 2025). "For example, the downregulation of NDRG1 is associated with tumor metastasis via inducing epithelial-mesenchymal transition; the expression of PPP2R1B was regulated by miRNA-587 to antagonizes 5-FU-induced apoptosis in CRC." (PMID 34233675, 2021). "Previous studies have reported that PPP2R1B is a tumour suppressor that plays a role in tumorigenesis." (PMID 38429738, 2024). "Last, we also observed strong correlations between eIF3a and PPP2R1B expression between tumor tissues from HPA and TCGA databases, further supporting our findings in cells." (PMID 34512348, 2021). "PPP2R1B is a constant regulatory subunit of protein phosphatase 2 and is a known tumor suppressor gene." (PMID 32101552, 2020). "In addition, a positive correlation between eIF3a and PPP2R1B expression was also observed in tumor samples from the Human Protein Atlas and TCGA databases." (PMID 34512348, 2021). "Moreover, several tumor suppressors, including BTG2, TUSC1, BAK1, LATS2, FZD6 and PPP2R1B, were regarded as common targets of TET3." (PMID 32209730, 2020). "Furthermore, we identified tumour suppressors, including BTG2, TUSC1, BAK1, LATS2, FZD6 and PPP2R1B, as common targets of TLX and TET3." (PMID 26838672, 2016). "A number of genes demonstrated reduced copy number and expression in KRAS mutant tumours, including putative tumour suppressor genes (FOXO3, EXTL2, PPP2R1B), negative regulators of the receptor tyrosine kinase oncogenic pathways (PTPRK, DGKZ, NCAM1), and negative regulators of Ras (EPHB2)." (PMID 21385341, 2011). "Three of the studies investigated reported on tumor tissue vs non-tumor tissue (GSE15471, GSE16515 and GSE101448), and in all these, we found an upregulation of KIAA1524/CIP2A, TIPRL, STRN and ARPP19, and a reduced expression of PPP2R1B in the tumor." (PMID 37170215, 2023).
cancer (17 papers, 2011 to 2025). A tumor composed of atypical neoplastic, often pleomorphic cells that invade other tissues. "In this study, we identified 9 cancer patients with germline loss-of-function (LOF) variants in PPP2R1B (Aβ), the β isoform of the PP2A scaffold subunit." (PMID 40178903, 2025). "Large-scale sequencing efforts identify multiple cancer patients with deleterious germline variants in PPP2R1B." (PMID 40178903, 2025). "Somatic mutations in PPP2R1A and PPP2R1B are frequently detected in cancer, and functional haploinsufficiency promotes tumorigenesis." (PMID 38502192, 2024). "Other PPP2R1B mutations have been detected in human hepatocellular carcinomas and are also found in melanoma and cancers of the breast and lung." (PMID 25867001, 2015). "Consistent with the hypothesis that Aβ loss may be an early event in cancer initiation, we identified 8 patients with germline LOF mutations in the Aβ gene PPP2R1B in a cohort of approximately 4000 cancer patients enrolled in the MI-ONCOSEQ study." (PMID 40178903, 2025). "PPP2R1B, the gene encoding the Aβ subunit of PP2A is located at 11q23 which is a chromosomal region that is frequently deleted in cancer cells." (PMID 25867001, 2015). "However, the mechanism of action of PPP2R1B in cancer progression is poorly understood, and the target substrate of PPP2R1B has not been verified." (PMID 38429738, 2024). "Moreover, Dinoi G and Cui J reported that PPP2R1B is related to cancer cell metastasis and drug resistance." (PMID 38429738, 2024). "PPP2R1B also specifically contributes to regulation of a signaling pathway downstream of RAS, by decreasing RalA phosphorylation and activity: thus, decreased PPP2R1B expression may contribute to increased cancer cell migration and EMT-high state." (PMID 37170215, 2023). "Furthermore, the relationship between eIF3a and PPP2R1B expression was detected in samples from patients with cancer." (PMID 34512348, 2021). "Moreover, point mutations or deletions of PPP2R1B were found to disrupt the binding of PP2Ac with PP2Aaβ in CRC patient tissues contributing to the deregulation of PP2A in CRC, though the frequency of PPP2R1B mutations in cancers is low." (PMID 38184584, 2024). "The mechanism of action for exosomal miR-200c is tubulin beta 3 Class III (TUBB3) and protein phosphatase 2 scaffold subunit Abeta (PPP2R1B) suppression, which decreases the migration, invasion, and motility of cancer cells." (PMID 36139487, 2022).
infection (2 papers, 2010 to 2021). The state of being infected such as from the introduction of a foreign agent such as serum, vaccine, antigenic substance or organism. "siRNAs that target PPP2R1B and/or PPP2R5E in Jurkat cells after Ad-TatSF2 infection caused a statistically significant decrease in apoptosis." (PMID 20862322, 2010). "mRNA levels of PPP2R1B and PPP2R5E were reduced by the PPP2R1B and PPP2R5E-specific siRNAs, respectively, but not by the control siRNA 24 hrs after infection." (PMID 20862322, 2010).
metabolic disorders (1 paper, 2025). "This study suggests a potential link between the aberrant expression of PPP2R1B caused by PM2.5 and the IRF3-mediated inflammatory responses that may contribute to the development of these metabolic disorders." (PMID 40711007, 2025).
PPP2R1B also shares sentences with these, for which no sentence is quoted: cervical carcinoma (2 papers); glioblastoma multiforme (1); hepatoma (1); Insulin resistance (1); Intellectual disability (1); Obesity (1); oesophageal cancer (1); ovarian carcinoma (1); pancreatic tumour (1); polycystic ovary syndrome (1); preeclampsia (1); skin cancer (1); testicular cancer (1); uveal melanoma (1).